CTLA4 (cytotoxic T-lymphocyte associated protein 4)
Diseases named in the same sentence as CTLA4 in open-access papers (continued):
Sharing a sentence is not in itself a finding about the gene and the disease.
tumor (continued). "Combined therapy, e.g., CTLA-4 and PD-1 checkpoint blockade, is a more effective treatment modality, but in preclinical studies OX40 agonism with CTLA-4 blockade using monoclonal antibodies (aOX40/aCTLA-4) failed to induce tumor regression of larger, more established tumors." (PMID 27330804, 2016). "Therefore, in our animal experiments, CTLA-4 blockade therapy was introduced, aiming at enhancing the anti-cancer therapeutic efficacy of ‘tumour vaccines' that are in situ generated after PLGA-ICG-R837-based photothermal ablation of primary tumours." (PMID 27767031, 2016). "In addition, immune checkpoint inhibitors like CTLA-4, the PD-1/PD-L1 axis, and CD40 could overcome the suppressive microenvironment of the tumour, and prevent T cell exhaustion and apoptosis." (PMID 27427766, 2016). "Antibody treatment with anti-CTLA-4 (p<0.02), anti-BTLA (p<0.01), anti- PD-L1 (p<0.01), anti- Lag-3 (p<0.001) and anti- PD-1 antibodies (p<0.02) led to a modest but a significant delay in tumor growth in MC-38 bearing mice (p values compared to mice that received isotype control antibody)." (PMID 27050669, 2016). "However, preclinical studies in multiple tumor models where antibodies to PD-L1, PD-1 and CTLA-4 are used as a monotherapy have not achieved much success." (PMID 27066484, 2016). "Because anti-CTLA-4 and anti-PD-1 promote intratumoral T cell infiltration, immune-checkpoint blockade prior to ACT may increase the number of TILs that can be derived from a tumor biopsy." (PMID 27847783, 2016). "This could explain why the majority of mice treated with α-CTLA-4 or α-PD-1 monotherapy delayed tumour growth but could not completely eradicate already-formed tumours." (PMID 27498556, 2016). "This triple combination—using OX40 agonism to step on the gas, CTLA-4 blockade to release the brakes, and vaccination using aDEC-205/HER2 to steer the immune response in the right direction—was able to generate profound CTL infiltration into the tumor leading to tumor regression." (PMID 27330804, 2016). "While blockade of CTLA-4 and PD-1 T cell checkpoints shows strong activity in a variety of cancers, many patients do not respond, likely due to insufficient spontaneous anti-tumor T cell immunity (a lack of tumor reactive T cells and/or poor T cell infiltration into the tumor)." (PMID 27660710, 2016). "One may envisage that such a decrease in intracellular CTLA-4 levels would decrease the T-cell activation threshold during contact with dendritic cells that express CD80 and CD86 and enhance their proliferation and anti-tumor abilities." (PMID 26110267, 2015). "Importantly, a minority of HCC tumors are spontaneously infiltrated by lymphocytes, and to date, HCC has not been one of the more responsive tumor types with checkpoint blockade with anti-CTLA-4 or anti-PD-1." (PMID 26199728, 2015). "More speculatively, recent advances in solid tumour immunotherapy using monoclonal antibody “check-point” inhibitors against CTLA4 and PD1/PD1L to reactivate anti-cancer cytotoxic immune defences show that active inflammation and active NK attack are integral to inducing tumour regression." (PMID 25615645, 2015). "Since CD80 binds CTLA-4 after T cell activation, we hypothesized that the observed lack of persistence and poor anti-tumor efficiency of 19z1-CD80+ T cells could result from CTLA-4 inhibition." (PMID 26110267, 2015). "The inhibitory receptors Programmed Cell Death Receptor 1 (PD-1) and Cytotoxic T-lymphocyte Antigen 4 (CTLA-4, also known as CD152) are inducible and expressed on activated T cells in response to various kinds of antigens such as tumor antigen presented by DCs or tumor cells." (PMID 25851535, 2015). "The route of administration may explain these differences as the same study showed that intratumoral administration of combined anti-OX40/anti-CTLA-4 did not affect Treg cells at a distant tumor site." (PMID 25763356, 2015).
tumor (continued). "Based on these results we have tested combination immunotherapy with α-CTLA-4 and α-PD-L1 antibody blockade in the K7M2 mouse model of metastatic osteosarcoma and show that this results in complete control of tumors in a majority of mice as well as immunity to further tumor inoculation." (PMID 25992292, 2015). "For Group 4 patients (CTLA-4high tumor cells, densitylow CTLA-4+ lymphocytes), CTLA-4 blockade alone would not induce an effective anti-tumor immunity given the paucity of preexisting TILs; combination therapies aimed at eliciting anti-tumor immunity are needed." (PMID 25893809, 2015). "Besides DC-CTL/CIK immunotherapy in this study, other immunotherapeutic agents also have made great progress in clinic, such as immune checkpoint inhibitor antibodies of PD-1/PD-L1 or CTLA-4, and chimeric antigen receptor-T cell (CAR-T) targeting specific tumor antigen." (PMID 26561538, 2015). "Collectively, the increased population of CD44hiCD8+ T cells in DC-immunized SKAP55−/− mice or ADAP−/− mice, which decreased PD-1 expression (but not CTLA-4) and increased granzyme B levels, might enhance the protection against tumor formation." (PMID 25851535, 2015). "Interestingly, their deficiency specifically suppresses PD-1 expression in CD8+ effector T cells without affecting CTLA-4 expression or the percentages of tumor-infiltrating CD4+Foxp3+ regulatory T cells (Tregs)." (PMID 25851535, 2015). "In contrast, a patient with low numbers of pre-existing tumor-specific T cells could have a delayed or no response to PD-1 or CTLA-4 pathway blockade." (PMID 25682878, 2015). "Since CTLA-4 and PD-1 regulate immune responses in a non-redundant fashion, combined blockade of both pathways may achieve more effective anti-tumor activity." (PMID 25538704, 2014). "First, we examined CTLA-4 expression in normal colon tissues, cultured CT26 cells, and CT26 tumor tissues from tumor-bearing BALB/c mice and BALB/c nude mice by reverse transcription polymerase chain reaction (RT-PCR) analysis and confirmed whether CTLA-4 is strongly expressed in CT26 tumor tissues." (PMID 25365349, 2014). "Then, we used RT-PCR to compare the expression of CTLA-4 and T cell markers in the CT26 tumor tissues of tumor-bearing BALB/c mice with those of tumor-bearing BALB/c nude mice in hopes of elucidating the relationship between CTLA-4 expression in the CT26 tumor tissues and T cells." (PMID 25365349, 2014). "Hence, immunotherapeutics that augment CD8 T-cell anti-tumor activity - such as anti-PD1 and anti-CTLA4 mAbs - given in combination with trastuzumab in patients with HER2+ BC may improve outcome by involving and enhancing critical host immunity." (PMID 25774617, 2014). "Immune-deprived mice bearing human tumor cell lines were not used because T cells might be responsible for the CTLA-4 expression in the tumor tissues." (PMID 25365349, 2014). "Therefore even with highly active drugs such as targeted therapy in the BRAF mutant population or with the new checkpoint inhibitors (CTLA-4 and PD-1/PDL-1 inhibitors) which potentiate the immune response in tumor, relapse at immune privileged sites will continue to be problematic." (PMID 25516805, 2014). "However, infiltrating CD8+ T cells often unable to show cytotoxic effect because, several tumor microenvironmental factors upregulate expression of inhibitory molecules like PD1 and CTLA4 on T cells to attenuate its effector functions and effector cytokine production." (PMID 25391149, 2014). "Interestingly, the abscopal effect observed at the secondary tumor sites was only in mice treated with the combination of CTLA-4 blockade and fractionated radiotherapy and not the single hypofractionated dose." (PMID 24324970, 2013). "In addition to the activity of anti-CTLA-4 mAb on lowering the threshold for activation of T cells in lymphoid organs, recent data suggest that some anti-CTLA-4 mAbs also can deplete Tregs within the tumor microenvironment." (PMID 24829752, 2013).
tumor (continued). "CTLA-4 expression is necessary for activation of self-regulation of T cells, and so CTLA-4 inhibitors could represent serious therapeutic options to generate T-cell hyperresponsiveness and overcome tumor immune escape." (PMID 23533766, 2013). "Results of CTLA-4 blockade in combination with one of various chemotherapeutic agents demonstrate that synergy occurs in settings where either agent alone was not effective in inducing tumor regression." (PMID 23873089, 2013). "However, the functional impact of anti-CTLA-4 therapy on human immune responses to tumor antigens is not yet fully understood." (PMID 22489248, 2012). "In patients receiving another CTLA-4 abrogating antibody, tremelimumab, the ratio of intratumoral T cells to FoxP3 positive T regulatory cells was increased after treatment only in regressing lesions, suggesting a therapeutic impact of CTLA-4 abrogation on T cells infiltrating the tumor." (PMID 22788688, 2012). "At present, there is no clear role for CTLA-4 blockade in the tumor microenvironment." (PMID 23087904, 2012). "Histological evidence indicates that anti-CTLA-4 activates the tumor vasculature and increases proliferation and infiltration of tumors by CD4+ and CD8+ (FoxP3-) effector cells, thereby increasing the ratio of effector T cells to Tregs in the tumor microenvironment." (PMID 21281484, 2011). "This might explain, why in vivo tumour prophylactic experiment with DC based vaccination against gp33 positive tumour cells did not clearly show an increased effect of CTLA-4 blockade despite increased CTL levels (data not shown)." (PMID 17662155, 2007). "Furthermore, CTLA4+ T cells secrete S100A4, which induces a stem-like phenotype in TNBC cells, while CD44 has been recognized as a stem cell marker in BC that binds multiple ECM components, notably hyaluronic acid (HA), modifying tumor behavior through co-receptor interactions." (PMID 41602418, 2026). "have shown that PD‐1 blockade or combination CTLA‐4/PD‐1 blockade, respectively, fails to support effector T cell differentiation in our models, further highlighting incomplete differentiation as a unique form of anti‐tumor T cell dysfunction distinct from exhaustion." (PMID 39930625, 2025). "Thus, we believe that pruning of dysfunctional non-HEV tumor blood vessels upon anti-CTLA-4 treatment, resulting from the anti-angiogenic effects of IFNγ, will lead to an increased functionality and a better perfusion of the remaining vessels, including TA-HEVs." (PMID 40460830, 2025). "Gene expression levels of FoxP3, CTLA4, and GITR were significantly higher in both unstimulated and PHA-stimulated PBMCs from BC patients compared to healthy controls, indicating heightened Treg cell activity that may contribute to tumor progression by suppressing anti-tumor immune responses." (PMID 40281554, 2025). "Notably, tumor-intrinsic checkpoint molecules such as PD-L1 can be regulated independently of immune infiltration, often upregulated through oncogenic or stress-response pathways such as p62–NRF2–mTORC1 signaling, even when PD-1 and CTLA-4 expression decline in immune-cold contexts." (PMID 41291343, 2025). "The association with IGSF8 may support immune cell recruitment and activation at inflammatory or tumor sites, whereas negative associations with CTLA4 and TIGIT imply a counter-regulatory effect on checkpoint pathways, potentially strengthening T-cell-mediated anti-tumor responses." (PMID 41180485, 2025). "In addition to inhibiting Treg function and restoring co-stimulatory signals from antigen-presenting cells, anti-CTLA-4 antibodies promote sustained activation of CD4+ and CD8+ effector T cells and mediate-Fc-dependent depletion of CTLA-4high Tregs specifically within the tumor microenvironment." (PMID 40558520, 2025).
tumor (continued). "Moreover, a high THEMIS2 expression was associated with increased levels of immune checkpoint molecules, such as PD-1, PD-L1, CTLA-4, and HAVCR2, indicating that THEMIS2 might contribute to establishing an immunosuppressive TME that facilitates tumor immune escape." (PMID 39851494, 2025). "In addition to PD-1, PD-L1, and CTLA-4, other inhibitory receptors—including T cell immunoglobulin and mucin-domain containing-3 (TIM-3) and lymphocyte activation gene-3 (LAG-3)—are increasingly recognized as markers and mediators of T-cell dysfunction within the tumor microenvironment." (PMID 40943541, 2025). "Critically, VTN expression correlated with key immunomodulators: positive associations with CXCL12 (a chemokine promoting T-cell recruitment) and negative trends with PD-L1/CTLA4 (immune checkpoint mediators) suggest that VTN may remodel the tumor immune microenvironment." (PMID 40433359, 2025). "In addition to classical immune checkpoints such as CTLA‐4 and PD‐1, as well as metabolism‐related molecules such as CD39/CD73, the chemokine receptor CCR8 has emerged as a highly promising therapeutic target because of its specific expression in tumor‐infiltrating Tregs (TI‐Tregs)." (PMID 41201063, 2025). "Moreover, compared to monotherapy of anti-CTLA-4 antibody, this combination treatment increased CD8+/CD4+ ratio in T cells and reduced the number of regulatory T cells and myeloid-derived suppressor cells within the tumor microenvironment, enhancing anti-tumor immunity." (PMID 40611940, 2025). "Despite the small sample sizes of these trials, the study of nivolumab plus ipilimumab demonstrated that ipilimumab was markedly effective in patients with cold tumors, supporting the theory that CTLA-4 blockade might be the most beneficial in patients lacking pre-existing anti-tumor immunity." (PMID 39561966, 2025). "Simultaneously, the high expression of immune checkpoint molecules like CTLA4 and TIGIT implies that Treg cells could establish an immunosuppressive state within the tumor microenvironment by suppressing the activation and proliferation of effector T cells, thereby facilitating tumor immune evasion." (PMID 41394809, 2025). "In this network meta-analysis, CTLA-4 inhibitors and cancer vaccines demonstrated a clear advantage in improving ORR, suggesting these modalities may elicit a stronger cytotoxic T-cell–mediated antitumor response capable of achieving radiographically detectable tumor shrinkage." (PMID 41293268, 2025). "Therefore, the increased Tregs in tumors from 16 Gy + anti-CTLA4 may be a negative feedback response to enhanced tumor infiltration by T cells." (PMID 39199612, 2024). "To understand the functional capacity of sCTLA-4 to modulate anti-tumor T cell responses, we constructed expression vectors to generate tumor cells that constitutively secrete recombinant sCTLA-4 and created stable cell lines but which, importantly, do not express surface CTLA-4." (PMID 38053333, 2024). "However, the blockade of CTLA-4 is accompanied by excessive activity of T cells, which not only enhances anti-tumor immune response but can also results in serious clinical toxic side effects, such as autoimmune diseases in the digestive system, liver, skin, and the nervous system." (PMID 39097732, 2024). "In addition to deciphering the tumor cells, efforts have been made to characterize the tumor immune microenvironment (TIME), improving the clinical benefit of immunotherapy, especially anti-PD-1/L1 and anti-CTLA4 antibodies; however, many patients still have poor outcomes." (PMID 38658971, 2024). "In addition, some tumors prompt regulatory T cells (Tregs) to express CTLA-4, leading to downregulation of CD80/CD86 expression in antigen-presenting cells, resulting in reduced production of cytokines such as interleukin 2, which affects the body’s anti-tumor capacity." (PMID 37622124, 2023).
tumor (continued). "Similarly, in the MC38 hot tumor mouse model, CCL20 and IL-1β also drove ILC3s infiltration and lymphocytes recruitment to inhibit tumor growth and also enhanced the reactivity to ICB including anti-PD-1 and anti-CTLA-4, significantly extending the survival rate." (PMID 37122757, 2023). "In addition, by binding to and increasing the expression of promoters such as Gal-1, PD-1, and CTLA-4, ZFP64 enables cancer cells to acquire stemness and resist immunosuppression; ZFP64 possesses the capability to affect tumor microenvironment and renders tumor cells resistant to immunosuppression." (PMID 37760477, 2023). "Current immune–checkpoint blockade (ICB)-based immunotherapies, commonly targeting PD-1, PD-L1 and CTLA-4, have not achieved the desired efficacy in the therapeutic practices in different types of cancers, suggesting that tumor cells may develop other ways to evade immune surveillance." (PMID 37504302, 2023). "Whether continued LTβR treatment in the absence of immune activation following treatment cessation of CTLA4 blockade + LTβR agonist is sufficient to maintain TA-HEVs and their lymphocyte aggregates which drive control of tumour growth was not determined in this work." (PMID 37287625, 2023). "Furthermore, scFv PD-L1 antibody decreased the expression of T cell exhaustion markers PD-1, TIM-3, and CTLA-4 in xenograft tumor models in vivo but not in cultured cells in vitro, suggesting that additional mechanisms are underlying the regulation of PD-1, TIM-3, and CTLA-4 expression in the TME." (PMID 36835603, 2023). "Importantly, by tracking the fate of labelled ECs following the cessation of CTLA4 blockade + LTβR agonist treatment, TA-HEVs were found to promptly transition back to a PCV state concomitant with a significant diminishment in CD3+ aggregates and tumour relapse." (PMID 37287625, 2023). "Therefore, pre-existing conditions might be prognostic markers for CTLA-4 blockade anti-tumour efficacy rather than post-treatment induced artifacts." (PMID 39086690, 2023). "Importantly, all these effects were obtained with negligible amounts of antibody released in the circulation and without any sign of discomfort in treated mice, minimizing the risk of toxicity without compromising the adjuvant and the anti-tumor effects of anti-CTLA-4." (PMID 37180141, 2023). "Furthermore, there were significant differences in the tumor-infiltrating immune population depending on whether or not lymph node treatment was performed after anti CTLA-4 therapy." (PMID 37539054, 2023). "Furthermore, single cell RNA sequencing revealed a high heterogeneity of tumor infiltrating CD8+ T cells in CTCL skin with a strong variation in the expression of co-inhibitory receptors PD1, CTLA4, TIM3, LAG3, and TIGIT, which could affect capacity of tumor cell killing." (PMID 37691935, 2023). "Indeed, CD8+ T cells in the tumor periphery showed increased expression of genes belonging to costimulatory pathways, including ICOS, TNFRSF4 (OX40) and TNFRSF9 (4-1BB), albeit accompanied by high levels of inhibitory receptors PDCD1 (PD-1), LAG3, HAVCR2 (TIM-3), and CTLA4." (PMID 38127790, 2023). "Second, ANG showed tight associations with most canonical immune checkpoints, such as PD1, CTLA4, and TIM3, suggesting that ANG might interact synergistically with these checkpoint members, all of which have been identified to play a suppressive effect on anti-tumor immunity." (PMID 37928479, 2023). "In addition, combination of mucin 1 (MUC1) mRNA nanovaccines with anti-CTLA-4 has also demonstrated enhanced antitumor effects against triple-negative breast cancer by improving the immunosuppressive tumor microenvironment (TME) and increasing CD8 + T cells, IFN-γ, and IL-12 levels." (PMID 37415161, 2023).